AURKA (aurora kinase A)
Diseases named in the same sentence as AURKA in open-access papers (continued):
Sharing a sentence is not in itself a finding about the gene and the disease.
prostate carcinoma (continued). "Similarly, AURKA is vastly overexpressed in all stages of prostate cancer (PCa), including castration-resistant PCa (CRPC) and neuroendocrine PCa (NEPC), although its transcripts are only increased in ~ 15% of cases, hinting at additional mechanisms of deregulation." (PMID 34625072, 2021). "We then used single-cell RNA sequencing to resolve the functional heterogeneity of AURKA in the PRAD epithelial cell subpopulation and verified its impact on the malignant phenotype of desmoplasia-resistant prostate cancer cells in in vitro experiments." (PMID 40718709, 2025). "In prostate cancer, HMMR promotes proliferation and metastasis via the mTORC2/AKT pathway by inhibiting ubiquitination and increasing AURKA levels in vitro and in vivo." (PMID 39196978, 2024). "We assumed that SNHG4 facilitates prostate cancer cell proliferation, the cell cycle and senescence by regulating RRM2, EZH2, AURKA and TK1." (PMID 37596700, 2023). "To substantiate the role of AURKA, we carried out in vitro experiments in esophageal adenocarcinoma (EAC), prostate cancer (PRAD), and pancreatic cancer (PAAD) cells." (PMID 37965456, 2023). "Overexpression of NK1R in epithelial prostate cancer cells was able to induce a shift of lineage plasticity, leading to the reduction of AR and PSA levels, the gain of the expression of CgA, ENO2, AURKA, N-Myc, MYT1, and SRRM4." (PMID 37385990, 2023). "In conclusion, IDOAMP directly inhibited Aurora kinase A and promoted the RIPK1/RIPK3/MLKL necrosome activation to inhibit the prostate cancer." (PMID 35965682, 2022). "Increased expression levels of both AURKA and AURKB have been observed in prostate cancer promoting cell proliferation and correlating with higher malignancy." (PMID 33572108, 2021). "To further confirm that WDR62 is a prostate cancer-specific regulator of the TPX2/AURKA protein complex, we examined WDR62, AURKA, TPX2 genetic dependencies in the DepMap." (PMID 34326322, 2021). "In 2011, Beltran and coworkers reported the frequent gene amplifications of MYCN and AURKA occurring in 40% of NEPC and 5% of prostate cancer adenocarcinomas, conferring a pronounced sensitivity of tumor cells to Aurora kinase inhibitors." (PMID 31366128, 2019). "A positive feedback loop has been described whereby AURKA induces MYCN and it has therefore been suggested that this cooperation leads to the prostate cancer phenotype." (PMID 28358317, 2017). "Recent molecular characterization of NEPC showed up-regulation of AURKA and MYCN expression and co-operative function to induce neuroendocrine differentiation in prostate cancer cells." (PMID 27015368, 2016). "Our study revealed a heterogeneity of AURKA expression in prostate cancer that was previously not identified." (PMID 40718709, 2025). "Notably, the high-expressing AURKA group showed a better prognosis in PSA-high and Gleason-low for prostate cancer patients." (PMID 40718709, 2025). "Furthermore, a phase 2 study indicated that amplification of AURKA and/or MYCN in prostate cancer conferred sensitivity to Aurora kinase A inhibition." (PMID 37025467, 2023). "UBE2C, PDZ-binding kinase (PBK), cyclin B1 (CCNB1), Cyclin-dependent kinase inhibitor 3 (CDKN3), topoisomerase II alpha (TOP2A), Aurora kinase A (AURKA) and MKI67 were identified as the candidate hub genes, which were all correlated with prostate cancer patient’ disease-free survival in TCGA." (PMID 33630978, 2021). "However, it has not been evaluated in prostate cancer (PCa), wherein AURKA is highly expressed in advanced stages and represents a critical therapeutic target." (PMID 41915443, 2026). "In particular, AURKA may serve as a compensatory pathway to support tumor activity after AR inhibition in prostate cancer, a complex mechanism not seen in other tumors." (PMID 40718709, 2025).
prostate carcinoma (continued). "Aurora kinase family members AURKA, AURKB and AURKC, have key functions to control mitotic progression in normal cells and are frequently overexpressed and dysregulated in several forms of cancer, including prostate cancer, contributing to progression of the disease." (PMID 35853811, 2022). "Subsequently, we studied AURKA protein expression in clinical samples with immunohistochemistry (IHC) in FFPE tissue samples representing 106 hormone naïve prostatectomies, 126 locally recurrent CRPC samples and 104 CRPC metastases from 31 patients who died of prostate cancer." (PMID 29269934, 2017). "We have also previously shown that the expression of AURKA is increased with androgen stimulation in LNCaP-ARhi cells expressing high levels of AR18, and ChIP-seq analyses have indicated a putative prostate cancer specific ARBS in the promoter as well as in the intronic region of the gene." (PMID 29269934, 2017). "However, a study of AURKA inhibitors in prostate cancer suggests that monotherapy with AURKA inhibitors is not effective in improving patient prognosis which may be partly due to compensatory survival pathways." (PMID 40718709, 2025). "The results showed that 7 genes were all associated with prostate cancer prognosis, but only UBE2C, TOP2A and CCNB1 were high expression in prostate cancer samples than normal prostate gland samples, the expression of PBK, CDKN3, AURKA, MKI67 were not." (PMID 33630978, 2021). "It is common for a NE prostate cancer phenotype to not express AR and PSA and common for amplification of the genes aurora kinase A (AURKA) and N-myc (MYCN, both of which were overexpressed in ACRJ-PC28 at RNA-seq level and MYC was detected at the protein level." (PMID 36643868, 2022).
colorectal cancer (63 papers, 2006 to 2026). A primary or metastatic malignant neoplasm that affects the colon or rectum. "AURKA inhibition or depletion is synthetically lethal in ARID1A-deficient colorectal cancer (CRC) cells as well." (PMID 39334449, 2024). "A recently published study revealed that targeting Aurora kinase A induced synthetic lethality in ARID1A deficient colorectal cancer cells." (PMID 36269546, 2022). "On the other hand, ARID1A has a synthetic lethal interaction with AURKA in colorectal cancer cells such that AURKA inhibition can selectively impede the growth of ARID1A-deficient colorectal cancer cells." (PMID 34737943, 2021). "In fact, elevated AURKA expression was observed in several human cancers, such as pancreatic cancer, endometrioid ovarian carcinoma and colorectal cancer liver metastasis, and was associated with poor prognosis." (PMID 33552715, 2021). "In fact, elevated AURKA expression was observed in several human cansers, such as pancreatic cancer, endometrioid ovarian carcinoma and colorectal cancer liver metastasis, and was associated with poor prognosis." (PMID 33750838, 2021). "Here, the authors show that ARID1A has a synthetic lethal interaction with AURKA in colorectal cancer cells and that ARID1A deficiency activates the AURKA target CDC25C, whose inhibitors also cause cell death in the ARID1A-deficient cell lines." (PMID 30097580, 2018). "Additionally, overexpression of AURKA in colorectal cancer liver metastases has been linked to poor outcomes." (PMID 38212708, 2024). "Another gene, Aurora kinase A (AURKA), is considered to be a pro-cancer enzyme in gastrointestinal tumors such as gastric and colorectal cancers." (PMID 40687837, 2025). "Ultimately, experimental validation through quantitative PCR in gastric and colorectal cancer tissue specimens confirmed that the transcript levels of AURKA, CEP55, DTL, and TTK are markedly elevated in tumor tissues compared to normal tissues." (PMID 40723362, 2025). "It was found that knockdown of AURKA significantly decreased growth of ES cells in vitro and in vivo, in line with previous reports that AURKA acts as an oncogene in various cancers, including gastric cancer, rhabdomyosarcoma, and colorectal cancer." (PMID 38287009, 2024). "AURKA inhibition holds promise as a therapeutic approach to overcome cetuximab resistance in RAS/RAF wild-type colorectal cancer, offering a potential means to counter the development of cancer stem cell phenotypes associated with cetuximab resistance." (PMID 38467828, 2024). "For example, AURKA is considered an oncogene that significantly impacts the proliferation and progression of colorectal carcinoma from colorectal adenoma." (PMID 36900162, 2023). "Contrary to these conclusions however, an exon II-dependent mechanism of AURKA translational activation was proposed for colorectal cancers in which both EGFR and AURKA are overexpressed." (PMID 36067794, 2022). "In this work, two exon II-containing transcripts (N#3 and N#5) were the major AURKA splicing isoforms expressed in human colorectal cancers." (PMID 36067794, 2022). "Another study focusing on Alisertib in colorectal cancer cell-lines, an AURKA inhibitor, also evoked a variability in cellular response independent of the genetic status of main known prognosis genes." (PMID 32138169, 2020). "The prognostic role of AURKA has ever been assessed in colorectal cancer patients by a research team in 2014." (PMID 32851091, 2020). "Though cancer stem cell is a small subpopulation of cancer cells, AURKA silencing sensitized the response of colorectal cancer stem cell (CR-CSC) to Oxaliplatin by upregulating antiapoptotic factors, which is different from our findings in colon cancer cells." (PMID 32851091, 2020).
colorectal cancer (continued). "Here we first performed differential expression analysis (DEA) of AURKA knockdown in two colorectal cancer (CRC) cell lines with 20q gain and AURKA overexpression." (PMID 29760449, 2018). "Here we show that ARID1A has a synthetic lethal interaction with aurora kinase A (AURKA) in colorectal cancer (CRC) cells." (PMID 30097580, 2018). "AURKA had the second highest number of reported amplifications in clinical samples with most of the cases being either breast or colorectal cancer cases (5 of 17 and 6 of 17, respectively)." (PMID 28371134, 2017). "AURKA overexpression was associated with the down-regulation of checkpoint with forkhead and ring finger domains (CHFR) in colorectal cancers with high microsatellite instability." (PMID 25987188, 2015). "Similarly, Aurora Kinase A (AURKA) promotes cell cycle progression and can be targeted in ARID1A-deficient colorectal cancer cells." (PMID 41278204, 2025). "Because overexpression of hnRNP Q1 positively correlated with AURKA overexpression in human colorectal cancer tissues, the authors suggest that hnRNP Q1 may contribute to the tumorigenesis of colorectal cancer via AURKA translational up-regulation." (PMID 36067794, 2022). "Another study reported that heterogeneous nuclear Ribo-Nucleoprotein Particle Q1 (hnRNP Q1), which is overexpressed in colorectal cancer and can promote cell proliferation, translationally up-regulates AURKA both in cap- and IRES-dependent manner via binding to AURKA 5′UTR." (PMID 36067794, 2022). "ARID3A facilitated the malignant phenotypes through upregulating AURKA in colorectal cancer." (PMID 35125116, 2022). "Liu found that knockdown of AURKA could lead to increased radiotherapy efficacy in human colorectal cancer." (PMID 34336648, 2021). "Phosphatase PRL-3 enhances AURKA ubiquitination and degradation in colorectal cancer." (PMID 33451333, 2021). "Aurora kinase A (AURKA) as a regulator of asymmetric satellite cell divisions, is a tumor suppressor with a high frequency of inactivating mutations in many cancers and the AURKA-CDC25C axis is a novel target for treating colorectal cancer." (PMID 34745136, 2021). "In addition, the expression level of AURKA was assessed in colorectal cancer (CRC) and gastric cancer (GC) samples." (PMID 34337875, 2021). "In this study, we hypothesized that high relative AURKA expression could predict sensitivity to FTY720-induced apoptosis in colorectal cancer (CRC)." (PMID 34768523, 2021). "Colorectal cancer (CRC) was one of the first cancers found to have AURKA amplification." (PMID 25987188, 2015). "This study reveals a phosphorylation‐dependent mechanism involving AURKA and highlights the FBXO44/FOXP1/Cyclin E2 axis as a potential therapeutic target in colorectal cancer." (PMID 41051444, 2025). "Previously, two basic studies about effectiveness of the combination of AURKA inhibitor and MEK inhibitor have been reported, one on melanoma cell lines and the other on colorectal cancer cell lines." (PMID 40546348, 2025). "AURKA, cyclin B1, and PLK1 proteins were highly upregulated in colorectal cancer SW480 and HCT‐116 cells compared with normal CCD841 cells." (PMID 38425293, 2024). "In colorectal cancer cells, ARID3A can bind with the AURKA promoter region and promote AURKA expression." (PMID 33451333, 2021). "One of its interacted genes, UBE2D1, a member of ubiquitin-conjugating enzyme E2D family, related to the Aurora kinase A (AURKA), which was an enhancer of Wnt and Ras-MAPK signaling in colorectal cancer (CRC)." (PMID 34946806, 2021). "In this study, using the cancer genome atlas (TCGA) data as well as colorectal cancer (CRC) and GC samples, AURKA expression levels were examined in 13 common cancers." (PMID 34337875, 2021). "Among them, we found that CCNA2, MAD2L1, DLGAP5, and AURKA were related to the overall survival (OS) of colorectal tumors, while RRM2 and AURKA had the relation between disease-free survival (DFS) and colorectal cancer." (PMID 33519906, 2020).
colorectal cancer (continued). "In our case-series, 38% of tumors showed a gain at 20q chromosome arm, where multiple candidate oncogenes associated with increased proliferative activity, reduced survival and progression of colorectal cancer (e.g. ZNF217, CYP24 and AURKA), are mapped." (PMID 22099067, 2011). "Furthermore, a previous study also demonstrated that the AURKA has the ability to enhance the Wnt and RAS signaling, which are usually hyperactivated in the colorectal cancer." (PMID 34565287, 2021). "Similarly, AURKA, BAG3, NUBP1, and ANLN are all found to be dysregulated in colorectal cancer and involved in cancer progression and invasion." (PMID 34790220, 2021). "In colorectal cancer, the RAS signaling has been reported to be activated by AURKA." (PMID 34565287, 2021). "Interestingly, while it was shown in colorectal cancer that AURKA regulates MEK/ERK pathway, it was reported that AURKA is a downstream target of this pathway in pancreatic cancer, raising the possibility of an existing positive feedback loop between AURKA and MEK/ERK pathway." (PMID 25987188, 2015).
gastric cancer (56 papers, 2001 to 2025). A primary or metastatic malignant neoplasm involving the stomach. "Next, we analyzed the association between AURKA and survival in 806 gastric cancer patients using Kaplan–Meier survival plots." (PMID 31740746, 2019). "Patients with AURKA haplotype variants exhibited high kinase activity and tended to develop advanced gastric cancer more readily." (PMID 31636670, 2019). "Logistic regression analysis of associations between AURKA rs2273535 polymorphism and risk of gastric cancer." (PMID 30174615, 2018). "In agreement, high AURKA expression was inversely associated with overall survival of gastric cancer patients and had been shown to be an independent prognostic factor for gastric cancer." (PMID 28218735, 2017). "Considering that co-overexpression of AURKA and Survivin was associated with poor prognosis of gastric carcinomas, we assessed the effect of Survivin expression on drug sensitivity." (PMID 28218735, 2017). "The polymorphism rs911160 in AURKA was identified to impact gastric cancer." (PMID 35201446, 2021). "Studies in recent years have also found that AURKA rs2273535 T>A polymorphism could enhance the susceptibility of gastric cancer." (PMID 31636670, 2019). "Stratified analyses between AURKA rs2273535 polymorphism and the risk of gastric cancer." (PMID 30174615, 2018). "Importantly, a previous study using comparative genomic hybridization array found that AURKA overexpression in high-risk primary gastric cancer tissues is associated with dysregulated expression of DNA damage response genes, which also include Survivin." (PMID 28218735, 2017). "Importantly, TUNEL assay showed that overexpression of AURKA reversed cell apoptotic death caused by doxorubicin in gastric cancer BGC823 cells." (PMID 28218735, 2017). "Since it has been shown that AR overexpresses in gastric cancer (GC) as a male-predominant tumor, the goal of this study was to evaluate the association between AR and AURKA and its prognostic value in GC patients." (PMID 31871591, 2019). "A study conducted in Korea revealed that the AURKA rs2273535 polymorphism was in strong LD with the rs1047972 genotype, and that patients with the AURKA haplotype variants had high kinase activity and a high risk of progression to advanced stage gastric cancer." (PMID 28152093, 2017). "AURKA and GSK3β interact with each other in gastric cancer cells, thereby enabling AURKA to phosphorylate GSK3β at S9, which inhibits its activity." (PMID 39334449, 2024). "Overexpression of AURKA has been observed in various tumor types, including breast, lung, colorectal, liver, and stomach cancers." (PMID 39834933, 2024). "Another study showed a direct positive correlation between RACGAP1 and AURKA in gastric cancer and that AURKA is also an important neuroendocrine (NE) marker of PCa." (PMID 37196108, 2023). "There is a direct positive correlation between RACGAP1 and AURKA in gastric cancer, and STAT3 and AURKA are all closely related to the neuroendocrine transformation of PCa." (PMID 37196108, 2023). "AURKA restricts survivin ubiquitylation and degradation in gastric cancer to promote drug resistance, and hence, the AURKA–survivin axis can be targeted to enhance the efficacy of DNA-damaging agents in treating gastric cancer." (PMID 36035159, 2022). "Aurora kinase A (AURKA) is highly overexpressed in gastric cancer and inversely correlated with prognosis." (PMID 36035159, 2022). "AURKA is reported to be involved in the progression of many kinds of cancers, such as gastric cancer and colon cancers." (PMID 32733789, 2020). "AURKA is activated in gastric cancer and it has been demonstrated that AURKA promotes cisplatin resistance in gastric cancer by regulating eIF4E, c-MYC, HDM2." (PMID 32508530, 2020). "Another study in gastric cancer demonstrated that AURKA promotes epithelial-mesenchymal transition through regulating Wnt/β-catenin and PI3K/Akt signaling pathways." (PMID 31871591, 2019).